CA9 (carbonic anhydrase 9)
Diseases named in the same sentence as CA9 in open-access papers (continued):
Sharing a sentence is not in itself a finding about the gene and the disease.
colorectal tumors (10 papers, 2010 to 2023). "This suggests, that not only CA9-, but also CA12 expression is associated with hypoxia in colorectal tumors." (PMID 36982873, 2023). "Thus, CA9 and CA12 seem to have no complementary roles in colorectal tumors but rather can also occur in a co-expressed manner." (PMID 36982873, 2023).
esophageal cancer (10 papers, 2008 to 2022). A primary or metastatic malignant neoplasm involving the esophagus. "In this study, we investigated CA9 expression in esophageal cancers and in precancerous lesions and explored the association of CA9 expression with prognostic factors and with stem cell and tumorigenesis-related markers including BMI1, cyclin E, ki67, MCM4 and MCM7 expression." (PMID 26156831, 2015). "Increased CA9 expression has been associated with decreased survival and cancer progression and has been targeted as a potential therapy for several cancers, including esophageal cancer." (PMID 26156831, 2015). "Since CA9 has been reported to functionally mediate tumor growth and metastasis, we investigated the relationship of CA9 and cyclin E expression in esophageal cancer." (PMID 26156831, 2015). "In addition, we confirmed that oesophageal cancer cells under hypoxic conditions proliferated faster than cells under normoxic conditions, suggesting that CA9 has a role other than pH regulation alone." (PMID 18841153, 2008).
soft tissue sarcoma (10 papers, 2011 to 2025). A malignant neoplasm arising from muscle tissue, adipose tissue, blood vessels, fibrous tissue, or other supportive tissues excluding the bones. "The clinical relevance of these findings is underscored by prior studies linking high expression of HIF-1α and CA9 to increased metastatic potential and poorer prognosis in soft tissue sarcomas." (PMID 41174561, 2025). "Carbonic anhydrase IX (CA9) has been proposed as a marker for poor prognosis in soft tissue sarcoma 99 and inhibition of CA9 sensitizes to ionizing radiation in certain type of cancers." (PMID 38434982, 2024).
head and neck squamous cell carcinoma (9 papers, 2005 to 2022). A squamous cell carcinoma that arises from any of the following anatomic sites: lip and oral cavity, nasal cavity, paranasal sinuses, pharynx, larynx, and salivary glands. "However, a later study demonstrated that a highly significant association of HIF-2α and CA9 was found in poorly differentiated head and neck squamous cell carcinomas." (PMID 26009875, 2015). "In a cohort study of head and neck squamous cell carcinoma, Based 9-gene model including CA9 was considered to be able to classify the disease for better clinical treatment." (PMID 33815132, 2021).
invasive carcinoma (9 papers, 2004 to 2022). A carcinoma that is not confined to the epithelium, and has spread to the surrounding stroma. "The CA9 upregulation ranges from 6-fold in adenocarcinoma and invasive carcinoma to an 11-fold change in the case of adenoma." (PMID 32707920, 2020).
sarcoma (9 papers, 2012 to 2024). A usually aggressive malignant neoplasm of the soft tissue or bone. "In the human sarcoma cell lines, CA9 was upregulated 18- to 36-fold, whereas FOXM1 remained relatively unchanged or slightly decreased." (PMID 22684860, 2013). "In the mouse sarcoma cell lines, CA9 was upregulated 24- to 49-fold, whereas FOXM1 levels again remained relatively unchanged or decreased slightly." (PMID 22684860, 2013). "Studies have shown that WNT7B, CA9, MMP13, and RAC3 are associated with poor outcomes in sarcomas." (PMID 36428766, 2022). "Considering pediatric sarcomas, our team previously reported that abundance of hypoxic markers (specifically SLC2A1 and CA9) in rhabdomyosarcoma characterized aggressive tumors resistant to neoadjuvant chemotherapy." (PMID 33810575, 2021). "In four sarcoma cell lines, HIF-1α shRNA or Dox at low concentrations blocked HIF-1α induction of VEGF-A by 84–97% and carbonic anhydrase 9 by 83–93%." (PMID 22684860, 2013). "The hypoxia response in terms of target genes was fairly similar between these sarcoma cell lines with uniform upregulation of VEGF-A and CA9." (PMID 22684860, 2013). "For the four sarcoma cell lines, VEGF-A and CA9 were upregulated in hypoxia." (PMID 22684860, 2013). "However, in terms of grading sarcomas, immunohistochemical studies for markers of vessels or proteins of pro-angiogenetic markers, such as HIF-1 and VEGF, or markers for a hypoxic condition such as carbonic anhydrase 9 or glucose transporter-1 have been reported to be useful, rather than US." (PMID 29619120, 2018).
bladder tumor (8 papers, 2002 to 2025). "Another novel finding from this study is that bladder tumours with low CD8+ T cell counts have higher CA9 expression (marker of tumour hypoxia), but that CD8+ T cell count retains independent prognostic significance in multivariable analysis." (PMID 36612036, 2022).
astrocytoma (7 papers, 2008 to 2022). "In terms of prediction of a survival benefit from bevacizumab, it has been reported that low CA9 expression was associated with better survival outcomes in patients with malignant astrocytoma treated with bevacizumab plus irinotecan." (PMID 19619339, 2009).
liver cancer (7 papers, 2015 to 2026). An epithelial or non-epithelial malignant neoplasm that arises from the liver. "Together, HBO downregulates the expressions of pH‐regulatory genes such as CA9 in H22 cancer cells, while CA9 is also associated with poor prognosis in liver cancer patients, suggesting that HBO might have the potential to regulate tumor pH and augment cancer treatment efficacy." (PMID 40873634, 2025). "Subgroup analysis based on specific glycolysis markers revealed that higher expression of PKM2 (P < 0.001), STMN1 (P = 0.002), MCT4 (P < 0.001), GLUT1 (P = 0.025), HK-2 (P < 0.001), and CA9 (P < 0.001) was significantly correlated with poor OS in liver cancer." (PMID 38114977, 2023). "In human liver cancer tissues, there was strong CA9 signal (hypoxia marker) in the area of platelet infiltration, but less in the area with weak CA9 signal." (PMID 32799418, 2020). "Building upon the preliminary confirmation that Metformin targets the protein CA9, we further conducted in vitro validation experiments using liver cancer cells to evaluate the therapeutic effects of Metformin alone and in combination with Lenvatinib on liver cancer." (PMID 40583627, 2025). "In this study, we employed a combination of in silico molecular docking and in vitro cell validation experiments to identify three ferroptosis suppressor genes, AR, HIF1A, and CA9, as promising components of a survival prognosis model during the metformin‐induced ferroptosis process in liver cancer." (PMID 40583627, 2025). "We analyzed data from three studies, including 636 patients, to investigate the correlation between PKM2, GLUT1, ASCT2, and CA9 expression levels and RFS in patients with liver cancer." (PMID 38114977, 2023). "The results indicated that glycolysis markers, including PKM2, STMN1, MCT4, GLUT1, HK-2, CA9, and GLUT2, can serve as potential prognostic biomarkers and therapeutic targets for liver cancer." (PMID 38114977, 2023). "High expression of PKM2 (P < 0.001), CA9 (P = 0.005), and MCT4 (P < 0.001) predicted a poor DFS in patients with liver cancer, as determined by subgroup analysis based on specific glycolysis markers." (PMID 38114977, 2023).
acute myeloid leukemia (6 papers, 2010 to 2022). Acute myeloid leukemia (AML) is a group of neoplasms arising from precursor cells committed to the myeloid cell-line differentiation. "In acute myeloid leukemia, the hypoxia-inducible factor-1 (HIF-1) targeting gene CA9 was associated with the clinical outcome." (PMID 36415514, 2022).
malignant glioma (6 papers, 2010 to 2023). A grade III or grade IV glioma arising from the central nervous system. "ScRNA‐seq analysis showed that the CA9 level significantly increased in the recurrent malignant glioma tumor cells compared with that in the primary malignant glioma." (PMID 37194413, 2023). "It is noted that malignant glioma cells can use CA9 to tolerate acidified microenvironment, while immune cells with tumor‐suppressive effects are useless for the tumor inhibition effects due to the acidic environment." (PMID 37194413, 2023). "Our experimental results suggested that M2‐like TAMs activated the PI3K/Akt/HIF‐1α/CA9 pathway in the malignant glioma cells via SPP1‐CD44‐mediated intercellular interaction to promote the recurrence of malignant glioma." (PMID 37194413, 2023). "The inhibition of CA9 expression reduces the tolerance of the tumor cells towards an acidic environment and prevents the invasion and metastasis of malignant glioma." (PMID 37194413, 2023). "The high expression level of CA9 is responsible to trigger the immunosuppressive response in the malignant glioma, thus promoting the degree of malignancy and drug resistance of recurrent malignant glioma." (PMID 37194413, 2023). "In the present study, we analyzed the inhibitory effects of two alternative HIF-1 targeting strategies, HIF-1α-siRNA and CTM, on HIF-1α expression and that of its target gene carbonic anhydrase 9 (CA9) in human malignant glioma cells." (PMID 21050481, 2010). "Interestingly, high expression of CA9 can trigger the immunosuppressive response in the malignant glioma, thus promoting the degree of malignancy and drug resistance." (PMID 37194413, 2023). "PI3K/Akt/HIF‐1α/CA9 activation promotes the recurrence of malignant glioma." (PMID 37194413, 2023). "The HIF‐1α/CA9 pathway provides a new therapeutic target for the treatment of malignant glioma." (PMID 37194413, 2023). "Moreover, the M2‐like TAMs can activate the PI3K/Akt/HIF‐1α/CA9 pathway in the malignant glioma cells via SPP1‐CD44‐mediated intercellular interaction." (PMID 37194413, 2023). "M2-like TAMs were found to increase in recurrent malignant glioma significantly and the M2-like TAMs could activate the PI3K/Akt/HIF-1α/CA9 pathway in the malignant glioma cells via SPP1-CD44-mediated intercellular interaction." (PMID 37612741, 2023). "Elevated VEGF-expression in recurrent malignant gliomas as determined by IHC, however, was associated with increased response rates to BEV but did not predict survival, whereas high expression of carbonic anhydrase 9 (CA9) was related to poor survival outcome." (PMID 26575171, 2016). "Results from this in vitro study suggest that inhibition of HIF-1α is a promising strategy to sensitize human malignant gliomas to radiotherapy and that CA9 could serve as an indicator of effective HIF-1-related radiosensitization." (PMID 21050481, 2010). "Therefore, intervention of CA9 expression through lncRNAs may be a novel research direction to inhibit the progression of malignant glioma." (PMID 37194413, 2023). "The results suggested that carboxyanhydrase 9 (CA9) was the downstream protein of HIF‐1α and was related to the immune microenvironment of malignant glioma." (PMID 37194413, 2023).
mesothelioma (6 papers, 2020 to 2025). A usually malignant and aggressive neoplasm of the mesothelium which is often associated with exposure to asbestos. "Hypoxia may aid cancerous mesothelioma cells in their defense towards ferroptosis by overexpressing the production of carbonic anhydrase-9 (CA9)." (PMID 35408533, 2022). "Indeed, it has been shown that carbonic anhydrase 9 (CA9), a well-known target of HIFs factors, can participate in mesothelioma cells ferroptosis resistance by regulating ROS, lipid peroxidation, and mitochondrial Fe2+ levels under hypoxia." (PMID 34539584, 2021).
tongue cancer (6 papers, 2015 to 2022). A malignant neoplasm affecting the tongue. "Carbonic anhydrase 9 (CA9) has been shown to be upregulated in the drug-resistant tongue cancer cell line Tca8113/PYM and to be associated with drug resistance." (PMID 25890268, 2015). "We have previously shown that overexpression of CA9 is associated with drug resistance in tongue cancer cells, although at that time the mechanism of CA9 upregulation was unclear." (PMID 25890268, 2015). "Importantly, a positive correlation was observed between ZEB1 and CA9 protein expression in tongue cancer tissues, and expression of these proteins associated with a poor prognosis for patients." (PMID 25890268, 2015). "We constructed a prognostic model based on a subset of the ferroptosis‐related genes and confirmed that one of these genes, CA9, is highly expressed in tongue carcinoma tissues." (PMID 34878732, 2022). "IHC analysis revealed that the expression level of CA9 in the tongue cancer tissues was significantly enhanced." (PMID 34878732, 2022). "We examined the specimens from 60 independent patients and compared CA9 expression between the tongue cancer and adjacent tissues by immunohistochemistry (IHC) analysis." (PMID 34878732, 2022). "Using COX regression model, we found that CA9 was highly related to tumour grade in tongue cancer patients." (PMID 32299152, 2020). "For instance, ZEB1 induces CDDP resistance in tongue cancer cells by transcriptionally activating carbonic anhydrase 9 (CA9)." (PMID 29849953, 2018). "In contrast, CA9 protein was strongly expressed in only 8 of 43 tongue cancer tissues that exhibited low ZEB1 protein expression." (PMID 25890268, 2015). "We now show here that ZEB1 predominantly correlates with drug resistance, mainly via modulating CA9 expression in tongue cancer cells." (PMID 25890268, 2015). "All the results denoted a potential correlation between ZEB1 and CA9 expression and their indication for the poor prognosis in human tongue cancer patients." (PMID 25890268, 2015). "Additionally, immunohistochemistry confirmed that CA9 was highly expressed in tongue carcinoma tissues, and a model based on ferroptosis‐related genes showed a good ability to predict overall survival in TSCC." (PMID 34878732, 2022). "The expression of CA9 was also verified by immunohistochemistry in tongue cancer samples." (PMID 34878732, 2022). "Finally, 60 cases of tongue carcinoma and normal tissues were collected, and immunohistochemistry was used to detect the expression of CA9." (PMID 34878732, 2022). "Notably, CA9 protein was strongly expressed in 39 of 41 tongue cancer tissues that exhibited high ZEB1 protein expression." (PMID 25890268, 2015). "Therefore, ZEB1 transcriptionally regulates CA9 expression to mediate chemoresistance in tongue cancer via modulating pHi in response to chemotherapy." (PMID 25890268, 2015). "ZEB1 expression was also found to promote CA9 expression in tongue cancer cells." (PMID 25890268, 2015). "ZEB1 bound to the promoter of CA9 to positively regulate CA9 expression in tongue cancer cells." (PMID 25890268, 2015). "CA9 may also be an important marker in the prediction of drug responsiveness in tongue cancer chemotherapy." (PMID 25789026, 2015). "In addition, high CA9 expression was also predictive of worse overall survival for tongue cancer patients." (PMID 25890268, 2015). "Next, we wished to determine whether ZEB1 modulates chemosensitivity in tongue cancer and whether it exerts its effect via regulating CA9 expression." (PMID 25890268, 2015). "Knockdown of CA9 abolished the chemoresistance resulting from ZEB1 overexpression and prevented maintenance of pHi mediated by overexpression of ZEB1 in tongue cancer cells." (PMID 32299152, 2020). "Given the role of CA9 in drug resistance and that ZEB1 regulates the expression of CA9, we further investigated the role of ZEB1 in the drug resistance of tongue cancer cells." (PMID 25890268, 2015).
tongue cancer (continued). "We have previously shown that both CA9 mRNA and protein expression is upregulated in the PYM-induced multidrug-resistant tongue cancer cell line Tca8113/PYM." (PMID 25890268, 2015). "We have previously shown that CA9 is involved in drug resistance in tongue cancer cells, and have shown here that ZEB1 positively regulates CA9 expression." (PMID 25890268, 2015). "We found that CA9 was strongly expressed in tongue carcinoma tissues and absent in adjacent tissues." (PMID 34878732, 2022). "Moreover, tongue cancer patients with both high ZEB1 and CA9 expression have worse overall survival compared to patients with both low ZEB1 and CA9 expression." (PMID 25890268, 2015). "In addition, through IHC, we found that CA9 was strongly positive in tongue cancer tissues but negative in adjacent tissues." (PMID 34878732, 2022). "Importantly, we found that ZEB1 protein expression strongly correlated with CA9 protein expression, and that the ZEB1–CA9 axis was a negative prognostic factor for overall survival in tongue cancer patients." (PMID 25890268, 2015).
dysplasia (5 papers, 2014 to 2018). A usually neoplastic transformation of the cell, associated with altered architectural tissue patterns. "In current study, we first explored the relationship of CA9 high expression with gastroesophageal reflux disease including columnar cell metaplasia, Barrett’s esophagus, low-and high-grade dysplasia." (PMID 26156831, 2015). "In a previous study, we observed that CA9 can be detected by immunohistochemistry in these lesions and, according to our series of cases, the absence of CA9 could exclude the possibility of dysplasia." (PMID 29745265, 2018).
lymphoma (5 papers, 2009 to 2025). A malignant (clonal) proliferation of B- lymphocytes or T- lymphocytes which involves the lymph nodes, bone marrow and/or extranodal sites. "Expression of CA9, but not PDPN, is found for several lymphoma cell lines." (PMID 39768175, 2024).
vulvar carcinoma (5 papers, 2011 to 2018). "Our approach was based on the simultaneous evaluation of the diagnostic capacity and sensitivity of specific epithelial markers, such as CK19 and CA9, which are constitutively expressed in cervical, endometrial and vulvar cancer, but not in normal lymph nodes." (PMID 24527437, 2014).
brain cancer (4 papers, 2013 to 2025). A primary or metastatic malignant neoplasm affecting the brain. "It has been reported that CA9 and CA12 are hypoxia-inducible in brain cancer." (PMID 23967163, 2013).
cholangiocarcinoma (4 papers, 2018 to 2019). A carcinoma that arises from the intrahepatic biliary tree (intrahepatic cholangiocarcinoma) or from the junction, or adjacent to the junction, of the right and left hepatic ducts (hilar cholangiocarcinoma). "Recently, CA9 and IDH1 were reported to be diagnostic factors for cholangiocarcinoma." (PMID 30849962, 2019).
clear cell carcinoma (4 papers, 2020 to 2025). "Immunostaining of the tumor revealed hepatocyte, arginase 1, CK20, CD10, CA9, and TFE3 negativity, along with AE1/AE3 and CK7 positivity, leading to the diagnosis of clear cell carcinoma of the liver." (PMID 41018392, 2025). "Immunohistochemical analysis showed positive staining for carbonic anhydrase 9 (CA9) but negative staining for cytokeratin 7 (CK7), consistent with clear cell carcinoma originating from the kidney." (PMID 32347406, 2020).
endometrial cancer (4 papers, 2014 to 2024). Primary or metastatic malignant neoplasm involving the endometrium (mucous membrane that lines the endometrial cavity). "We confirmed that exposure of endometrial cancer cells to 3% O2 for 24 hours was sufficient to increase the expression of hypoxia-dependent genes (CA-9, VEGF and Glut-1)." (PMID 31819173, 2020).